MCL1 (MCL1 apoptosis regulator, BCL2 family member)
Diseases named in the same sentence as MCL1 in open-access papers (continued):
Sharing a sentence is not in itself a finding about the gene and the disease.
acute myeloid leukemia (149 papers, 2007 to 2026). Acute myeloid leukemia (AML) is a group of neoplasms arising from precursor cells committed to the myeloid cell-line differentiation. "Conversely, low and high levels of NOXA, which binds MCL1 to reduce its anti-apoptotic buffering potential, was associated with venetoclax resistance and sensitivity, respectively, in acute myeloid leukemia." (PMID 40858806, 2025). "In this preclinical study, we assessed the HSP90 inhibitor PU-H71 in combination with the MCL1 inhibitor S63845 or the BCL2 inhibitor venetoclax in the treatment of acute myeloid leukemia and investigated the associated biomarkers of response." (PMID 37754227, 2023). "Elevated Mcl-1 expression has been linked to the development of acute myeloid leukaemia in human cells." (PMID 33632038, 2021). "Mcl-1 has been implicated in the development of diverse malignancies, including those of hematopoietic origin such as MM, mantle cell lymphoma, and acute myelogenous leukemia." (PMID 24594907, 2014). "In addition, we also evaluated the protein levels of BCLxL (encoded by BCL2L1) and MCL1 in 12 acute myeloid leukemia lines that express both proteins." (PMID 30635584, 2019). "Similar findings in acute myeloid leukemia (AML) showed apoptosis induction directly correlating with Mcl-1 loss, underscoring the therapeutic potential in Mcl-1–dependent malignancies." (PMID 41149606, 2025). "Acute myeloid leukemia samples with higher MCL1 and NAMPT gene expressions, and higher monocytic cell content present increased likelihood of poor intrinsic ex vivo response to venetoclax." (PMID 40222279, 2025). "Despite promising anti-leukemic activity of MCL-1 inhibitors in preclinical studies of acute myeloid leukemia (AML), clinical progress has been hindered by limited knowledge of target patient subgroups." (PMID 40975877, 2025). "Along with Bcl-2, other anti-apoptotic proteins, such as Mcl1 and Bcl-xL, play a critical role in the survival of cancer cells in other hematological malignancies, such as acute myeloid leukemia (AML) and multiple myeloma (MM)." (PMID 39684550, 2024). "BH3 mimetic antagonists to BCL-2 and MCL-1 has been considered as an anti-tumor strategy to induce cell death in acute myeloid leukemia (AML), and resistance to BH3 mimetics has been identified as a critical clinical problem." (PMID 39035027, 2024). "MCL-1 has been reported to be overexpressed in multiple myeloid malignancies like multiple myeloma and acute myeloid leukemia." (PMID 38571491, 2024). "Overexpression of MCL-1 is frequently observed in many types of malignancies, including solid tumors and hematological malignancies such as acute myeloid leukemia (AML) and multiple myeloma (MM)." (PMID 36986673, 2023). "Previous studies have confirmed that MCL1 can promote cell migration and invasion in some types of cancers, including renal cell carcinoma, acute myeloid leukemia, and pancreatic ductal adenocarcinoma." (PMID 37900961, 2023). "Translation-level loss of Mcl1 and cell death upon GSK3 inhibition was recently reported for Acute Myeloid Leukemia (AML) cell lines." (PMID 36291813, 2022). "In the present study, PTC596 decreased MCL1 levels in MM cells in acute myeloid leukemia and mantle cell lymphoma." (PMID 33483574, 2021). "Previous studies have reported that PTC596 increases mitochondrial apoptosis through the reduction of Mcl-1 expression in acute myeloid leukemia progenitor cells and mantle cell lymphoma." (PMID 34576269, 2021). "S63845 potently kills MCL-1-dependent haematological (e.g. multiple myeloma, acute myeloid leukaemia (AML)) and some solid cancers, as a single agent or in combination with other anti-cancer agents." (PMID 34515749, 2021). "We have previously reported that inhibiting MCL‐1 expression with S63845 produces a synergistic apoptotic response when used in combination with venetoclax in acute myeloid leukaemia (AML) cells." (PMID 35846088, 2021).
acute myeloid leukemia (continued). "In proof of principle studies, we demonstrated that MCL1 silencing in acute lymphoblastic leukemia (ALL) and acute myeloid leukemia (AML) PDX models correlates to response to pharmacological MCL1 inhibition." (PMID 34580292, 2021). "In acute myeloid leukaemia cell lines, 3 inhibits RNA polymerase II phosphorylation, supresses Mcl-1 and XIAP and induces apoptosis." (PMID 33632038, 2021). "This is particularly marked in breast carcinoma cancer cell lines, with MCL1‐ and MARCH5‐dependent cells having similar sensitivity to haematologic cancer cell lines (acute myeloid leukaemia), where MCL1 inhibitors are in clinical development." (PMID 32627965, 2020). "Overexpression of BCL-2, BCLXL, and MCL1 frequently occurs in acute myeloid leukemia (AML) conferring resistance to conventional chemotherapy." (PMID 33230098, 2020). "Actually, the downregulation of Mcl-1 through GSK3β activation contributed to As2O3-induced apoptosis in acute myeloid leukemia." (PMID 31121982, 2019). "Here we found that the MCL1-inhibitor S63845 and the MEK-inhibitor trametinib specifically target primary cells of acute myeloid leukemia with elevated MCL1- and MEK-protein levels." (PMID 31718075, 2019). "Mcl-1 is known as a crucial component in As2O3-induced apoptosis through GSK3β activation in acute myeloid leukemia." (PMID 31121982, 2019). "In alignment with our findings, sunitinib was active against acute myeloid leukemias (AML) possessing activating PDGFR, FLT-3, and c-kit mutations through inhibiting mTOR and reducing Mcl-1 levels." (PMID 29066973, 2017). "MCL-1 was previously identified by our group and others as mediator of resistance against cytotoxic drugs in acute myeloid leukemia (AML) but also against antigen-specific cytotoxic T-cells in solid tumor models." (PMID 28507280, 2017). "It has also been demonstrated that MAPK inhibition led to Mcl-1 down-regulation that sensitized acute myeloid leukemia to ABT-737 action." (PMID 25627260, 2015). "The pan-Bcl-2 inhibitor (−)B197D6 induced apoptosis of acute myeloid leukemia (AML) cells by disrupting Mcl-1/Bim and Bcl-2/Bax interactions." (PMID 26405162, 2015). "Sorafenib, a potent multikinase inhibitor, induces apoptosis of human acute myeloid leukemia (AML) cells through downregulating Mcl-1 and enhancing binding of Bim to Bcl-2 and Bcl-xL." (PMID 26405162, 2015). "It has been reported that downregulation of Mcl-1 through GSK-3β activation contributes to chemically-induced apoptosis in acute myeloid leukemia cells." (PMID 24585095, 2014). "Accumulated evidence indicates that Mcl-1 is essential for development and survival of acute myelogenous leukemia and various solid tumors including CCA." (PMID 24742042, 2014). "This event is not due to cell cycle arrest but to the induction of apoptosis, probably via a mechanism involving the MCL-1 downregulation, as already demonstrated in acute myeloid leukemia." (PMID 20003259, 2009). "Moreover, the cooperative function of Bcl‐2 and Mcl‐1 has been identified as a mechanism leading to treatment failure in acute myeloid leukemia (AML), where dual inhibition of these proteins has shown potential to improve treatment results." (PMID 40405831, 2025). "Targeting the FLT3 receptor and the IL-1R associated kinase 4 as well as the anti-apoptotic proteins MCL1 and BCL2 may be a promising novel approach in the treatment of acute myeloid leukemia (AML)." (PMID 38666914, 2024). "Venetoclax and Metformin synergise in acute myeloid leukaemia by downregulating MCL1." (PMID 38928195, 2024). "These include the Bcl2-selective BH3-mimetic Venetoclax, which is currently used for the treatment of chronic lymphocytic leukemia, small lymphocytic lymphoma, or acute myeloid leukemia, or the myeloid cell leukemia-1 (Mcl-1) inhibitors S63845, AMG-176, and AZD5991." (PMID 38275765, 2024).
acute myeloid leukemia (continued). "In this preclinical study, we assessed the IRAK4 inhibitor emavusertib (CA4948) in combination with the MCL1 inhibitor S63845, the BCL2 inhibitor venetoclax, and the HSP90 inhibitor PU-H71 in the treatment of acute myeloid leukemia and investigated the associated biomarkers of response." (PMID 38666914, 2024). "Furthermore, a novel class of Mcl-1 inhibitors has the potential to be developed for the treatment of acute myeloid leukemia." (PMID 36782330, 2023). "AZD-5991 is a macrocyclic molecule with high selectivity and affinity for Mcl-1, due to the fact that it binds directly to Mcl-1; it induces rapid apoptosis in cancer cells, most notably MM and acute myeloid leukemia, via activation of the Bak-dependent mitochondrial apoptotic pathway." (PMID 35884390, 2022). "Upon analysis of patient data, MCL1 amplification was significantly correlated with a fatty acid β-oxidation gene signature in two independent acute myeloblastic leukemia datasets, suggesting a link between MCL1 upregulation and fatty acid β-oxidation metabolism in cancer." (PMID 34475520, 2021). "HPF is also able to elicit growth arrest and caspase-dependent apoptosis in acute myeloid leukemia (AML) cell lines and in primary AML cells, in which the apoptotic mechanisms are again traced back to mitochondrial membrane potential loss, Noxa overexpression and Mcl-1 downregulation." (PMID 33379141, 2020). "Moreover, combining BH3-mimetics to target both BCL-2 and MCL1 had potent activity in pre-clinical models of acute myeloid leukemia and in T-cell acute lymphoblastic leukemia cells." (PMID 31718075, 2019). "CR alone shows down regulation of MCL-1 in acute myelogenous leukemia." (PMID 29899871, 2018). "Moreover, miR-29 targets Mcl-1 in human hepatocellular carcinoma cells and acute myelogenous leukemia cells, and its expression is down-regulated in both types of cancer." (PMID 23894561, 2013). "B-cell lymphoma 2 (BCL-2) and other BCL-2-like family members of proteins such as BCL-XL and MCL-1 are highly expressed in leukemia such as acute myeloid leukemia (AML) and account for treatment resistance to chemotherapeutics." (PMID 35326111, 2022). "In acute myeloid leukemia (AML), breast cancer cell lines and primary AML cells, fadraciclib has demonstrated actions that decreased RNA Pol II phosphorylation, reduced Mcl-1 level, and induced apoptosis." (PMID 35383271, 2022). "For instance, the combination of venetoclax and MCL-1 inhibitor produced a synergistic apoptotic response in acute myeloid leukemia (AML) cells in vitro compared to the administration of venetoclax alone." (PMID 34198580, 2021). "It has shown promising anticancer activity as an Mcl-1 inhibitor, rendering it usable as a treatment of multiple myeloma (MM) and acute myeloid leukemia (AML)." (PMID 34834084, 2021). "Bcl-2 inhibitors display an effective activity in acute myeloid leukemia (AML), but its clinical efficacy as a monotherapy was limited in part owing to failure to target other antiapoptotic Bcl-2 family proteins, such as Mcl-1." (PMID 32699295, 2020). "The PI3K/AKT/mTOR pathway is known to promote cell survival through translational control of Mcl-1 in acute myeloid leukemia (AML)." (PMID 31121982, 2019). "Since in acute myeloid leukemia the combination of idasanutlin with venetoclax results in an accelerated downregulation of MCL1 and subsequent induction of apoptosis, the same might hold true in neuroblastoma, providing an alternative explanation for the synergistic effects of this drug combination." (PMID 28915653, 2017). "Anti-apoptotic protein Mcl-1 plays an important role in protecting cell from death in acute myeloid leukemia (AML)." (PMID 25714024, 2015). "Studies on human acute myeloid leukemia (AML) cells have also suggested that Obatoclax mediates the release of Bim and Bak from Mcl-1, resulting in release of cytochrome-c and apoptosis of AML cells." (PMID 24367627, 2013).
acute myeloid leukemia (continued). "In acute myeloid leukemia cell lines, venetoclax combined with alvocidib (CDK9 inhibitor) reduced cell viability while reducing Mcl-1 levels." (PMID 40704654, 2025). "Acute Myeloid Leukemia (AML) remains a critical therapeutic challenge, warranting the development of novel inhibitors targeting essential survival proteins such as Myeloid Cell Leukemia-1 (Mcl-1)." (PMID 40979648, 2025). "Similar to the synergism observed between obatoclax, a Mcl-1/Bcl-2 inhibitor, and TRAIL, another Mcl-1/Bcl-2 antagonist, venetoclax, showed synergism with the TRAIL fusion protein, eftozanermin alfa, in acute myeloid leukemia cells, as well as in patients." (PMID 41180258, 2025). "However, their effectiveness in acute myeloid leukemia (AML) is limited by compensatory MCL-1 accumulation via the ubiquitin proteasome system." (PMID 39924517, 2025). "A structure‐guided peptide derived from a non‐canonical amino acid library simultaneously targets MCL‐1 and BCL‐xL to overcome apoptotic resistance in acute myeloid leukemia." (PMID 40305693, 2025). "A next-generation BH3 toolkit aims to deliver durable apoptotic control in acute myeloid leukemia (AML) while mitigating the class-defining liabilities of thrombocytopenia from BCL-XL antagonism and cardiotoxicity from sustained MCL-1 suppression." (PMID 41347170, 2025). "MCL-1 and BCL-2 are typically overexpressed in acute myeloid leukemia and are required for the survival of AML cells and stem cells." (PMID 38790277, 2024). "MCL1 (myeloid cell leukemia-1) is a closely related to BCL2 (B-cell lymphoma 2) and both frequently overexpressed in acute myeloid leukemia and critical for the survival of AML cells and AML stem cells." (PMID 35895695, 2022). "As such, Mcl-1 specific inhibitors, such as AMG 176, can synergise with BH3 mimetics to achieve tumour regression in acute myeloid leukemia (AML) tumour models." (PMID 33627786, 2021). "Myeloid cell factor-1 (MCL-1) is a death inhibiting member of the BCL-2 family which is highly expressed in B-cell chronic lymphocytic leukemia (B-CLL), acute myeloid leukemia (AML), and acute lymphoblastic leukemia (ALL)." (PMID 32645846, 2020). "Indeed, acid CDase was found to be overexpressed in acute myeloid leukemia (AML) patients, modulating Mcl-1 expression, while its inhibition sensitizes cells to chemotherapeutics." (PMID 33048123, 2020). "Many acute myeloid leukaemias (AMLs) express high levels of BCL-2 and MCL-1, especially after therapy." (PMID 30470795, 2019). "Recent reports indicate that cells derived from acute myeloid leukemia (AML) patients can be effectively targeted with a BCL-2 and/or MCL-1 inhibitor, although other studies suggest that these cells depend primarily on BCL-2 for survival." (PMID 30185825, 2019). "Acute myeloid leukaemia (AML) cells often up-regulate pro-survival members of the BCL-2 protein family, such as BCL-2 and MCL-1, to avoid apoptosis." (PMID 30701031, 2018). "The overexpression of anti-apoptotic Bcl-xL, Mcl-1 or Bcl-2 occurs frequently in cancers, particularly in hematologic malignancies such as acute myeloid leukemia (AML) and multiple myeloma (MM), resulting in defective apoptosis leading to enhanced cell survival and drug resistance." (PMID 28038464, 2017). "When overexpressed in acute myeloid leukaemia cells, the survival proteins BCL-2 and MCL-1 confer chemoresistance." (PMID 27092880, 2017). "The multikinase inhibitor sorafenib could synergize with Obatoclax in inducing apoptosis in acute myeloid leukemia (AML) through downregulating Mcl-1." (PMID 23431463, 2013). "Genomes of acute myeloid leukemia (AML) cells resistant to the BCL-2–selective inhibitor venetoclax (VEN) show extensive differential methylation with the activation of the RAS/MAPK pathway, leading to increased stability and higher levels of MCL-1 protein." (PMID 38279330, 2024).
acute myeloid leukemia (continued). "Earlier experiments in acute myeloid leukemia (AML) cell lines support our results, reporting that MCL-1 levels were downregulated by azacitidine and that this resistance mechanism could be overcome by additional BH3 mimetic treatment with ABT737." (PMID 37945692, 2024). "Together, these data indicated that high-UNC93B1 expressed AML cells shows greater dependence on MCL1 than BCL2 for survival, and UNC93B1 might be a biomarker to predicting drug response in acute myeloid leukemia." (PMID 36741319, 2023). "Our best compound was acylsulfonamide 7d with a Ki of 800 nM against MCL-1 and 1.82 mM against BCL-xL, and demonstrated an improved effect on the viability of the HL60 acute myeloid leukemia cell line relative to the parent carboxylic acid-containing dual inhibitor from which it was derived." (PMID 38024975, 2023). "Among the potential candidates, MCL1, a protein belonging to the Bcl-2 family that plays critical anti-apoptotic roles, attracted our attention since it confers MDR in acute myeloid leukemia and is also positively related to drug resistance in several types of cancer." (PMID 33816494, 2021). "The MCL1 inhibitor S63845 and the MEK inhibitor trametinib may be effective therapeutic compounds in acute myeloid leukemia." (PMID 31718075, 2019). "miR-181b increases drug sensitivity in acute myeloid leukemia via targeting HMGB1 and Mcl-1." (PMID 32309578, 2016). "In addition, selective inhibition of MCL1 has been shown to induce apoptosis in acute myelogenous leukaemia cell lines without signs of toxicity to normal human haematopoietic progenitor cells." (PMID 30261081, 2018). "In addition, and in contrast to previous reports in acute myeloid leukemia cells, we did not observe a downregulation of MCL1 protein levels upon treatment with idasanutlin." (PMID 28915653, 2017). "Targeting the molecular chaperone HSP90 and the anti-apoptotic proteins MCL1 and BCL2 may be a promising novel approach in the treatment of acute myeloid leukemia (AML)." (PMID 37754227, 2023). "Amplification and overexpression of the myeloid cell leukemia differentiation protein MCL1 and the murine double minute protein MDM2 have been reported in various human tumors as well as hematological malignancies including acute myeloid leukemia (AML)." (PMID 31718075, 2019). "Thus, inhibition of SPHK1 in human acute myeloid leukemia cells, but not the inhibition of SPHK2, induces MCL-1 degradation." (PMID 37020867, 2023). "In support of the idea that targeting antiapoptotic Bcl-2 proteins with BH3 mimetics may increase NK cell-mediated cytotoxicity, a recent report has described that inhibition of Mcl-1, but not Bcl-2, increased the therapeutic efficiency of NK cells against acute myeloid leukemia (AML) cells." (PMID 34374809, 2022).